CD81 (CD81 molecule)
Diseases named in the same sentence as CD81 in open-access papers (continued):
Sharing a sentence is not in itself a finding about the gene and the disease.
infection (continued). "HCVpp infection remained CD81 dependent even when claudin-1 was overexpressed in Hep-G2 (CD81 negative cell line, becomes susceptible to HCVpp upon expression of CD81) cell line." (PMID 19643019, 2009). "Lines expressing low levels of CD81 were refractive to infection and showed only background levels of luciferase activity, in keeping with previous studies which show that productive HCVcc infection requires a minimal level of CD81 expression." (PMID 19088272, 2009). "However, since Huh-7w7/mCD81 cells are susceptible to HCVcc and HCVpp-2a infection, we next took advantage of this model and the MT81w mAb to study the role of TEM-associated CD81 in the early steps of HCV life cycle." (PMID 19476617, 2009). "Treatment with an anti mouse CD81 mAb (MT81) prevents infection by this parasite." (PMID 18389082, 2008). "Indeed, antibodies to CD81 or CD81 silencing strongly reduce the infection of hepatocytic cells by P. yoelii (a rodent parasite) and P. falciparum (a human parasite) sporozoites." (PMID 18389082, 2008). "Moreover, most recently CD81 was shown to be required for the infection of primary hepatocytes by serum-derived HCV." (PMID 18382656, 2008). "Additional chimeras were generated to determine whether other CD81 residues in either the A or the B helix contribute to the ability of CD81 to support infection by P. yoelii sporozoites." (PMID 18389082, 2008). "If CD81 was a receptor for a sporozoite protein, it would be expected that mAbs that require this region for the recognition of CD81 are the most potent at inhibiting infection." (PMID 18389082, 2008). "Furthermore, a construct where CD9 LEL was exchanged with CD81 LEL (CD9LEL81) was also able to support infection to the same extent as CD81, pointing out the importance of CD81 LEL." (PMID 18389082, 2008). "When cells are transfected with hCD81, they remain susceptible to infection despite MT81 treatment because the anti-mouse CD81 mAb does not recognize hCD81 (which can functionally replace mCD81 in this model)." (PMID 18389082, 2008). "We then tested whether 5A6 could inhibit the infection of HepG2-A16 cells stably expressing CD81 by P. yoelii sporozoites." (PMID 18389082, 2008). "Finally, to assess the involvement of 5-HT2AR in HCV cell entry in vivo, we evaluated the ability of ezetimibe to inhibit infection of a genotype 2a (JC-1) in immune-competent humanized transgenic mice of chronic HCV infection harboring both human CD81 and OCLN genes (C/OTg)." (PMID 29542010, 2019). "Specifically, the L216F mutation (as well as two other mutations in the hypervariable region 1, HVR1) allow infection of cells expressing CD81 of rodent origin, suggesting that HCV adaptation to new hosts does not necessarily entail changes at the direct binding interface with CD81." (PMID 29765366, 2018). "Additionally, the observation that IDPP retained an inhibitory effect stronger than a α-CD81 antibody when given 2 h post-infection indicated that IDPP may act on additional steps in the HCV life cycle." (PMID 28333153, 2017). "HCV initiates infection by attaching to molecules or receptors at the cell surface and current evidence supports an essential role for scavenger receptor class B member I (SR-BI), tetraspanin CD81 and tight-junction proteins claudin-1 and occludin in clathrin-dependent particle endocytosis." (PMID 25667327, 2015). "Furthermore, this can also be achieved in a mouse model deficient in CD81 where hepatocytes are non-permissive to productive infection." (PMID 23255300, 2013). "Furthermore, we next assessed whether this anti-CD81 mAb can prevent viral spread when added post-infection." (PMID 23704981, 2013). "Indeed, anti-CD81 antibodies were able to block infection in vitro and in a mouse model." (PMID 22174670, 2011).
infection (continued). "However, we found that PDZK1 knockdown was associated with a moderate yet significant reduction in the susceptibility of HepG2(N6)+CD81 cells to HCVcc (Jc1/Myc) infection (not shown)." (PMID 20949066, 2010). "Indeed, a chimera in which the end of the A helix and the B helix of CD9 were substituted by the 21 corresponding residues of CD81 (CD9[81B]: VVDDDANNAKAVVKTFHETLD) could support infection by P. yoelii sporozoites to the same extent as CD81ccg9." (PMID 18389082, 2008). "This study has uncovered a new functionally important region of CD81 and, by comparing the ability of several CD81 antibodies to block infection, has strengthened the hypothesis that CD81 might regulate the function of another molecule present at the hepatocyte surface during Plasmodium infection." (PMID 18389082, 2008). "Thus, to strengthen the conclusion that the CD81 A and B helices in a CD9 backbone are sufficient to render HepG2-A16 cells susceptible to infection, CD81ccg9 and CD9ccg81 chimeras were stably expressed in HepG2-A16 cells and compared to cells stably expressing CD81." (PMID 18389082, 2008). "In this hypothesis, not all CD81 molecules but only those that associate with this particular molecular partner would be functionally competent for infection." (PMID 18389082, 2008). "Comparative analysis using the MACSplex EV kit revealed a significant reduction in the tetraspanins CD63, CD81 and CD9 in sEVs derived from Salmonella-infected macrophages (obtained at 24- and 48- hours post-infection) relative to uninfected controls." (PMID 40895579, 2025). "Having confirmed the integrity of CD81 KO 293T and THP-1 cells, we next assessed early gene product expression (by ICP4 staining), as well as virus growth (by plaque assay), following infection with HSV-1." (PMID 40780411, 2025). "These include murine genes incompatible with HCV biology (CD81, OCLN, TRIM26, CypA) and those murine factors that actively inhibit infection (CD302, CR1L)." (PMID 40899815, 2025). "These examples illustrate the protective roles of CD81 and the PI3K/AKT pathway in T cells during various human infections, highlighting their importance in maintaining effective immune responses." (PMID 39329713, 2024). "Compelling evidence indicates that the large extracellular loop (LEL) of mast cell-expressed TET proteins [Cluster of differentiation (CDs), such as CD9, CD63, CD81, CD82, CD151] plays a key role in the route of pathogens infection." (PMID 35310653, 2022). "Interestingly, we observed not only a reduced number of infection events in scenario 1 for both cholesterol-binding mutants, but also a reduction of CD81-dsRNA colocalization events (77% reduction for CD81 E219A and 46% for CD81 E219Q compared to wild-type CD81)." (PMID 35612284, 2022). "Ablation of CD81 results in decreased CHIKV permissiveness, while overexpression enhances infection." (PMID 35612284, 2022). "Here, we observe that CD81 is dispensable for CHIKV entry and is instead required during later steps of the infection cycle, i.e., RNA replication." (PMID 35612284, 2022). "CD63 on progeny HIV-1 surface was also found to interfere with infection, and this interference was extended to other tetraspanins (CD9, CD81, CD82, and TSPAN7)." (PMID 34769038, 2021). "Our results are consistent with these findings, suggesting that trafficking of CD81 within MDDCs to the plasma membrane and recruitment to TEMs, along with HIV-1, are required for trans-infection." (PMID 32075937, 2020). "CD81, a type II transmembrane protein, is one of the main tetraspanins recruited to the host cell membrane during HIV-1 trans-infection and is known to colocalize with HIV-1-containing compartments in macrophages and DCs." (PMID 32075937, 2020). "As before, we transduced Huh-7 CD81 KO cells with each of our CD81 mutants and then challenged with J6/JFH HCVcc, quantifying the resultant infection by microscopy." (PMID 32900848, 2020).
infection (continued). "The tetraspanin CD81 colocalizes with HIV-1 within VCC and accumulates at the VS, promoting viral trans-infection, preventing cell-to-cell fusion, and providing a platform for viral budding." (PMID 32075937, 2020). "HCV exploits several cell-surface molecules for cell entry, but only two of these (CD81 and OCLN) determine the species-specificity of infection." (PMID 29765366, 2018). "The LELs of CD63, CD81 and CD151 induced a minor, but significant reduction of HPV infection rates in HeLa and HaCaT cells at 24 h post infection (h.p.i.)." (PMID 30279342, 2018). "In this study, the general requirements of the tetraspanins CD9, CD63, CD81, and CD151 in infections by the most oncogenic HPV type, HPV16, were tested as previously investigated for HCMV." (PMID 30279342, 2018). "This systematic approach revealed that CD81, CD44, CD98, caveolin-1 and catenin delta-1 were down-regulated during infection whereas GRP-78 was up-regulated." (PMID 29121670, 2017). "We assessed the inhibitory activity of our anti-CD81 EC2 mAbs against HCVcc and determined the concentration of each mAb required to inhibit infection by 50% (IC50)." (PMID 29090272, 2017). "Infection with HCMV TB40 and HSV-1 downmodulated the tetraspanins CD81, CD151, and CD9, as well as EGFR." (PMID 29121670, 2017). "This cell line lacks cell surface expression of CD81, which enables the assessment of HCV replication and infectious virus production by removing the influence of re-infection by progeny viruses." (PMID 27703205, 2016). "We carried out inhibitory assays using a CD81-specific antibody and the NS5B polymerase inhibitor 2’CMeA for infection with culture medium inoculation." (PMID 27678340, 2016). "Anti-CD81 mAb reduced HCVpp-H77 and HCVpp-JFH1 infection of Huh7.5, PHH and HLMF cells by more than 50%, demonstrating that infection was CD81-dependent." (PMID 26214688, 2015). "The inhibitory effects of anti-CD81 antibody and IFN-a were also found in parallel in Huh7.5 and PHH infection by HCVcc and." (PMID 26214688, 2015). "Infection was inhibited by polyclonal patient IgG from pooled HCV-infected donors, neutralizing anti-CD81, Telaprevir (VX-950) and interferon-α." (PMID 25701818, 2015). "We conclude that these vesicle-like structures can be identified using CD81, as shown here and elsewhere, and they play a crucial role in HIV-1 entry into astrocytes, whilst also supporting trans-infection of neighboring cells." (PMID 24587404, 2014). "The results of our study suggest that the CD81 compartment can harbor and protect HIV-1 whilst also acting as a vehicle to facilitate trans-infection of neighboring cells." (PMID 24587404, 2014). "We found that antibodies targeting CD81, CLDN1, and the OCLN EC2-F5 mutant blocked infection when added either pre- or postbinding, indicating that these agents block postbinding HCV cell entry events." (PMID 23555257, 2013). "In agreement with the previous findings showing downregulated expression of OCLN and CLDN-1 in Huh7 cells after infection with JFH-1 HCVcc, the level of OCLN and CD81 expression significantly decreased in Jurkat T cells infected with native HCV." (PMID 23626783, 2013). "The remaining antibodies targeting CD81, CLDN1, and OCLN all continued to strongly inhibit infection when added after the binding phase, indicating these factors are post-binding HCV cell entry factors." (PMID 23555257, 2013). "Collectively, these results demonstrate that both MAbs neutralize infection in a dose-dependent manner and indicate that the entry of our cell culture adapted HCV occurred in an E2- and CD81-dependent way." (PMID 23940646, 2013). "At 20 minutes post infection, the mean fraction of virus particles colocalized with early endosomes (marked by EEA1) was ∼50% and ∼53% for control and CD81-knockdown cells, respectively." (PMID 24130495, 2013).
infection (continued). "The subsequent interactions between E2 and other cell surface receptors and/or co-receptors, including CD81, claudin, occludin, and SR-BI, probably stabilize HCV attachment and therefore result in specific infection of hepatocytes." (PMID 23844141, 2013). "As there were differences in infection efficiencies of HCVcc and HCVpp between these cell lines, we analyzed cell-surface expression of the HCV receptor, CD81, using flow cytometry." (PMID 23285155, 2012). "While analyzing the regulation of IFN induction pathway by ISG15 in JFH1-infected Huh7.25/CD81 cells, we noticed that the expression of ISG15, as well as ISG56, another IRF3‐responsive ISG, increased in response to JFH1 infection in the Huh7.25/CD81 cells." (PMID 23202496, 2012). "Both infections of Huh7.5 cells – that by J6/JFH1 and that by serum viruses – were effective and were neutralized by α-CD81 antibodies." (PMID 21887279, 2011). "In accord with this, depletion of endogenous Ube1L from the Huh7.25.CD81 cells, as such or after ectopic expression of ISG15, UbcH8 and HERC5, resulted in an increase in IFNβ induction after infection with HCV." (PMID 22022264, 2011). "HCV envelop protein E2 posses glycosylation sites which interact directly with the cell surface receptors CD81, SR-BI and CLDN1, confirming their role in HCV entry by using HCVpp or HCVcc infection in liver cell lines." (PMID 21896165, 2011). "Although our lentivirus transfection efficiency with CD81 was around 95% in IPK and IRK clones, only 1% of the cells were prone to infection with HCVcc." (PMID 21731692, 2011). "We compared the ability of Huh7.25/CD81, Huh7.5 and Huh7 cells to activate the IFN inducing pathway after transfection with an IFNβ-luciferase reporter and infection with Sendai virus." (PMID 20485506, 2010). "Using Huh7.25.CD81 cells that ectopically express TRIM25, we observed that HCV triggers IFNβ induction as early as 6 hrs after infection, demonstrating that the entry of the virus into the cell rapidly generates enough viral structured RNAs to activate RIG-I." (PMID 20485506, 2010). "First, ectopic expression of TRIM25 triggered a significant inhibition of virus yields at 24 hrs post-infection (40%), as expected from its ability to restore IFN induction in Huh7.25/CD81 cells as shown in previous figures." (PMID 20485506, 2010). "To estimate the time-frame required to study IFN induction before its abrogation upon the action of NS3/4A, we first established the kinetics of MAVS cleavage in the two HCV permissive cell lines Huh7.25/CD81 and Huh7.5 following HCV infection." (PMID 20485506, 2010). "The authors concluded their results point to CD81 and SRBI functioning cooperatively during the infection process." (PMID 19643019, 2009). "Binding of E2 occurs at the CD81 LEL and binding of E2 to CD81, or infections with HCVpp or HCVcc, are inhibited with pretreatment with CD81 LEL or antibody versus CD81." (PMID 19643019, 2009). "The infection of 293T cells by HCVpp was enhanced 10 fold with the over-expression of SRBI, and SRBI anti-serum reduced HCVpp infectivity of Huh7 and CD81+ HepG2 cells in a dose dependent manner." (PMID 19643019, 2009). "They play a role in the infection by several viruses including HIV and CD81 is essential for the infection of hepatocytic cells by the hepatitis C virus (HCV)." (PMID 18389082, 2008). "We have previously reported that the tetraspanin CD81, a known receptor for the hepatitis C virus (HCV), is required on hepatocytes for infection by sporozoites of several Plasmodium species." (PMID 18389082, 2008). "For example, RNAi silencing of CD81 or CD151 reduces HCV replication, while doxycycline-induced knockdown of CD9, CD63, and CD81 increases ZIKV replication; conversely, their overexpression limits infection." (PMID 41157594, 2025).
infection (continued). "In accordance with the literature, we therefore hypothesize that CD81 may also be expressed on fused PHEV-EVs and facilitate exosomal fusion with the target cell, thus enhancing the overall infection." (PMID 41059972, 2025). "Finally, we also present evidence that CD9/CD81/CD63+ EVs, including LC3+ EVs subset, represents a novel cell-free mechanism for dengue virus dissemination following infection of DCs." (PMID 38863700, 2024). "However, of note, when using the two viral genomes devoid of inducing a spreading infection, we consistently observed higher numbers of HCV-expressing cells in the CD81KO cells in comparison to the CD81-positive Huh7.5 controls." (PMID 38357447, 2024). "Similarly, and relevant to our study, CD81 and PI3K/AKT pathways play a significant role in the survival and proliferation of T cells during infection including viruses like influenza virus infection." (PMID 39329713, 2024). "Indicating that the ectopic huLiver model had infection levels that were similar to those seen in the FRG-huHep mice and that the increase in CD81 and EphA2 receptor expression in the HC-04 cell line did not improve infection efficiency." (PMID 36928885, 2023). "Complementation with the PyB9 propeller domain restored infection in both HepG2 cells, which express SR-B1 but not CD81, and HepG2/CD81 cells, which express both receptors, suggesting that the B9 propeller domain does not restrict host cell receptor usage." (PMID 36761022, 2023). "In addition, CD9 only enhanced infection of the CHIKV ECSA genotype, which is highly dependent on CD81." (PMID 35612284, 2022). "Moreover, CD63, CD81 (transmembrane proteins), and HSP70 (cytosolic proteins) all showed positive results in both control and infection groups, indicating the presence of exosomes in terms of marker proteins for their general characterization." (PMID 36059498, 2022). "Moreover, coexpression of CD81 and CD9 led to similarly low infection rates with this Asian genotpye as observed in Lunet cells lacking CD81 and CD9 or Lunet cells expressing CD9 only." (PMID 35612284, 2022). "We detected slightly more infection events for scenario 2 in cells expressing CD81 (66% versus 59% in cells lacking CD81) and slightly less dsRNA signal in the cytoplasm when CD81 was present (14% versus 23% in cells lacking CD81, scenario 3)." (PMID 35612284, 2022). "Previous studies have shown that the human hepatocarcinoma HepG2 cells express SR-BI but not CD81, and as a consequence, they support infection by P. berghei but not by P. falciparum or P. yoelii sporozoites." (PMID 34268141, 2021). "Hence, lowering tetraspanin CD81 and/or CD63 expression or blocking their activity during early infection seems to be a promising strategy to limit reverse transcription, genomic integration, and ultimately viral replication." (PMID 34769038, 2021). "All three tetraspanins—CD9, CD63, and CD81—were present in BEVs irrespective of infection or treatment status." (PMID 33036231, 2020). "Antibodies that prevent this interaction block HCV entry, and cells without CD81 are completely resistant to infection (35, –, 44)." (PMID 32900848, 2020). "Taken together, these data suggest that trafficking of CD81 and p24 Gag to the cell periphery to form the TEM is compromised by knockdown of ARF1, BIN-1, RAB7L1, and RAB8A, potentially preventing the efficient trans-infection of virus via the VS." (PMID 32075937, 2020). "Further support for this conclusion was obtained from measurements of HCV infection of receptor knock-out cells; modest infection occurred in SR-B1 KO cells, whereas no infection was detected in the absence of CD81." (PMID 30883541, 2019). "To test whether additional tetraspanins are involved in HPV16 infection, we applied a pseudovirus (PsV) infection assay, depleting either CD9 or CD81." (PMID 30279342, 2018).